MUC5B (mucin 5B, oligomeric mucus/gel-forming)
Diseases named in the same sentence as MUC5B in open-access papers (continued):
Sharing a sentence is not in itself a finding about the gene and the disease.
breast carcinoma (23 papers, 2012 to 2025). "MUC5B expression is disrupted in breast cancers and is associated with increased cell proliferation and metastasis of breast cancers and can be explored as a cancer biomarker and a therapeutic target." (PMID 37454130, 2023). "Secreted mucin MUC5B has been reported to be associated with poorer prognosis of lung adenocarcinoma patients and lead to aggressive behavior of breast cancer cells." (PMID 29179459, 2017). "Notably, increased MUC5B expression is associated with increased aggressive behavior of breast cancer and colorectal cancer." (PMID 36831639, 2023). "In conclusion, MUC5B expression is associated with aggressive behavior of MCF7 breast cancer cells." (PMID 23056409, 2012). "The mucin MUC5B has a critical protective function in the normal lung, salivary glands, esophagus, and gallbladder, and has been reported to be aberrantly expressed in breast cancer, the second leading cause of cancer-related deaths among women worldwide." (PMID 23056409, 2012). "MUC5B (mucin-5B), a glycoprotein variably expressed in gastric and breast cancers, is reduced in higher-grade ovarian tumors." (PMID 41373846, 2025). "For example, MUC5B expression is related to the aggressive behavior of breast cancer cells, and when the expression of MUC5B was silenced, the proliferation, clonogenicity, and adhesion ability of the breast cancer cells were decreased." (PMID 37770976, 2023). "MUC5B has been identified as a signature of invasive mucinous adenocarcinoma and was highly expressed in gastrointestinal, pancreatic, and breast cancer." (PMID 37726835, 2023). "MUC5B, which we found up-regulated in LUAD and down-regulated in LUSC, has also been associated with an aggressive profile in breast cancer." (PMID 31429720, 2019). "To understand further the implication of MUC5B in breast cancer pathogenesis, we transfected MCF7 cells with a recombinant mini-mucin MUC5B, and we evaluated the invasive and metastatic potential of these cells in vitro and in an s.c. xenograft model." (PMID 23056409, 2012). "Among the four polymerizing mucins MUC2, MUC5B, MUC5AC, and MUC6 whose altered expression has been reported in breast cancer tissues, the role of MUC5B is poorly documented." (PMID 23056409, 2012). "We have reported previously that all mammary tumors develop spontaneously in the transgenic MMTV-ras mouse strain produced Muc5b." (PMID 23056409, 2012). "In this context, the MUC5B gene might be considered as a potential candidate gene for targeted therapy in epithelial-derived mammary tumors in both humans and dogs." (PMID 41168812, 2025). "In addition, abnormal expression of MUC5B has been shown in other cancers such as gastric carcinomatous tissues and breast cancer tissues." (PMID 35572847, 2021). "Functional studies of MUC5B also revealed that MUC5B could promote breast cancer MCF7 cells proliferation and metastasis." (PMID 29670111, 2018). "Mucins or mucin-like glycoproteins MUC5B and MUCL1 are often deregulated in cancer and are reported to have higher expression in breast cancer than normal tissue." (PMID 40597443, 2025). "A study reported high frequencies of MUC5B protein in breast cancer tissues, whereas mucin was not expressed in normal breast samples." (PMID 41168812, 2025). "In mammary tissue, MUC5B protein is detected with a high frequency in breast cancer tissues, whereas the mucin is not expressed in normal control breast samples." (PMID 23056409, 2012). "MUC5B and MUCL1 (also known as Small Breast Epithelial Mucin/SBEM) have both been shown to drive invasion in vitro and are associated with poor survival and metastasis in breast cancer patients, although there are no reports on effects in ILC." (PMID 40597443, 2025).
interstitial lung disease (23 papers, 2013 to 2026). A diverse group of lung diseases that affect the lung parenchyma. "This study aimed to characterize single nucleotide polymorphisms (SNPs) in TOLLIP and MUC5B among patients with interstitial lung disease (ILD) and its subtypes." (PMID 42058428, 2026). "We first tested for a known disease association with the MUC5B regulatory polymorphism (rs35705950) and interstitial lung diseases." (PMID 38991590, 2024). "Whole genome sequencing thus corroborates the association of rs35705950 with MUC5B dysregulation and interstitial lung disease." (PMID 25192356, 2014). "IPF is a heterogeneous interstitial lung disease caused by abnormal host-defense, activation of immune and non-immune cells, and dysfunctional wound, male gender, cigarette-smoking, and mutations in MUC5B and Sftpc gene confer a predisposition to the development of IPF." (PMID 32549377, 2020). "Recently, a polymorphism in the promoter of MUC5B, the gene encoding mucin 5B, has also been associated with interstitial lung disease regardless of smoking history." (PMID 24707414, 2014). "We recruited 405 patients with interstitial lung diseases (ILD), including 165 IPF patients and 2043 healthy controls, for genotyping the MUC5B gene in the Chinese population." (PMID 25121989, 2014).
cystic fibrosis (22 papers, 2011 to 2026). Autosomal recessive disorder caused by pathogenic variants in the CFTR gene (cystic fibrosis transmembrane conductance regulator), which encodes a chloride and bicarbonate channel expressed in epithelial cells, and follow the diagnosis criteria. "The impact of mucus rheology is particularly significant in conditions such as cystic fibrosis, where the accumulation of thick, cross-linked MUC5B and MUC5AC impairs mucociliary clearance and exacerbates infection and inflammation." (PMID 41158440, 2025). "While MUC5B is thought to be more associated with COPD and cystic fibrosis, MUC5AC production is more likely to be relevant to the pathophysiology of asthma." (PMID 39057040, 2024). "We found that PEGylation does not make the differencewhen the mucus barrier properties are dominated by pathology-associatedproteins, such as the gel-forming mucins MUC5AC and MUC5B (i.e., sputumfrom cystic fibrosis patients)." (PMID 35107987, 2022). "MUC5AC and MUC5B are involved in the pathogenesis of respiratory infectious diseases, such as cystic fibrosis and chronic obstructive pulmonary disease, and contribute considerably to amplification of inflammation and tissue injury." (PMID 22768318, 2012). "The MUC5B-specific activity of MdpS2 suggests that it could be particularly useful for targeted interventions in cystic fibrosis." (PMID 41158440, 2025). "Mucus accumulation and airway mucus plugging are part of cystic fibrosis pathophysiology and the total mucus concentration as well as the staining intensity for MUC5AC and MUC5B were elevated in bronchioalveolar lavage fluid from children with cystic fibrosis compared to age matched controls." (PMID 36927357, 2023). "In muco-obstructive airway diseases like cystic fibrosis, immune cells and bacteria release enzymes that degrade MUC5B into smaller fragments that become entangled and compacted, contributing to pathogenesis." (PMID 42240337, 2026). "MUC5B is produced at baseline in the lungs and MUC5AC is upregulated in response to a challenge, an infection, as well as a chronic lung condition like cystic fibrosis." (PMID 36117114, 2023). "For instance, the major gel-forming mucins MUC5B and MUC5AC in the sputum of cystic fibrosis patients display a distinctive glycosylation pattern, characterized by reduced sulfation, increased sialylation, and decreased fucosylation." (PMID 41257290, 2025).
rheumatoid arthritis (16 papers, 2020 to 2025). A chronic, systemic autoimmune disorder characterized by inflammation in the synovial membranes and articular surfaces. "However, studies interested in other autoimmune diseases such as rheumatoid arthritis have shown an association with the MUC5B promoter variant." (PMID 40630118, 2025). "The risk factors for developing RA-ILD are smoking, elevations of rheumatoid factor and anti-citrullinated protein antibodies, presence of rheumatoid nodules, elevated erythrocyte sedimentation rate, longer RA duration and presence of the MUC5B promoter variant." (PMID 36551792, 2022). "In patients with rheumatoid arthritis, MUC5B rs35705950 T risk allele carriership has recently been shown to have a significant contribution to the prediction of subclinical RA-ILD disease." (PMID 36552935, 2022). "By contrast, IIP associated variants have also been found in rheumatoid arthritis-ILD, and for the MUC5B variant at least, specifically with an underlying usual interstitial pneumonia (UIP) pattern." (PMID 31916109, 2020). "The most studied is the MUC5B promoter gene rs35705950, which has been found in patients with IPF, FPF, rheumatoid arthritis (RA)-ILD, and fibrotic HP." (PMID 40363955, 2025). "From a pathobiological perspective, it was reported that the mechanisms of fibrosis in non-IPF ILDs, including rheumatoid arthritis (RA)-ILD and HP, have commonalities with IPF such as MUC5B single nucleotide polymorphism and short telomere length." (PMID 34719401, 2021).
Airway obstruction (13 papers, 2011 to 2025). Obstruction of conducting airways of the lung. "The importance of MUC5B is indicated by Muc5b-deficient mice, which showed an accumulation of undesired substances e.g., bacteria, resulting in severe inflammation and airway obstruction." (PMID 32411147, 2020). "MUC5B is essential for mucociliary clearance from the airways, and alterations in the amount, glycoform, and morphology of MUC5B have been associated with airway obstruction." (PMID 26993521, 2016). "Histology, immunohistochemistry, and micro-computed tomography imaging studies identified airway obstruction with MUC5B-positive mucus plugs in neonatal Slc26a9-/- mice." (PMID 41105627, 2025). "Muc5AC and Muc5B gene expression in obstructive lung diseases have been dissected in numerous studies, and notably in cigarette smoke exposure models." (PMID 35269434, 2022). "Out of two principal mucus forming enzymes, MUC5a and MUC5b, the overproduction of MUC5a has a major contribution to airway obstruction." (PMID 35296330, 2022). "It will be important to determine the site of synthesis of Muc5ac and Muc5b in horses with airway obstruction to inform future therapeutic developments targeted at modulating mucin production in horses with respiratory disease." (PMID 21602926, 2011). "Second, under conditions of high inflammatory burden and epithelial barrier disruption, excessive MUC5B expression may stabilize mucus networks and promote mucus cast formation, thereby sustaining airway obstruction." (PMID 41561092, 2025). "Muc5b-deficient mice do not clear the aspirated materials from the airways, develop chronic bacterial infections, severe inflammation, and airway obstruction." (PMID 38259471, 2023). "The alterations in mucin composition we observed, namely increased MUC5AC and low-charge MUC5B, may contribute to a pathologic mucus gel with altered mucus biophysical properties leading to airway obstruction." (PMID 28716644, 2017). "MUC-5B is a major component of airway secretions, plays a critical role in COPD pathogenesis, where its abnormal overexpression leads to excessive mucus production, further exacerbating airway obstruction." (PMID 40604933, 2025). "Additionally, IL-17A and IL-17 F stimulate airway epithelial and smooth muscle cells to produce mucins (MUC5B and MUC5AC), enhancing mucus hypersecretion and contributing to airway obstruction." (PMID 39850030, 2024). "Importantly, in a study of COPD, the relative amounts of MUC5AC and MUC5B were shown to differ in smokers with and without airway obstruction, suggesting that the mucin composition of mucus is a major factor for efficient mucus transport." (PMID 21602926, 2011). "While mucins MUC-5AC and MUC-5B are the principal secreted mucins found in the airways of healthy individuals, their levels are substantially elevated in patients with moderate COPD compared to both non-smokers and smokers without airway obstruction." (PMID 40604933, 2025).
fibrosis (13 papers, 2019 to 2025). the formation of excess fibrous connective tissue in an organ or tissue in a reparative or reactive process. "Some instrumental SNPs have been shown to be closely associated with IPF, for example, the specific mutation rs35705950 (MUC5B) associated with fibrosis." (PMID 37502356, 2023). "Mutations in the genes encodingtelomerase reverse transcriptase (TERT) and mucin5B (MUC5B) are well-known risk factors forpulmonary fibrosis." (PMID 36912407, 2023). "Murine studies suggest a causative role for ER stress in AT2 cell dysfunction, and ER stress is a proposed connection between IPF and multiple fibrosis risk factors including aging, the MUC5B risk allele, hypoxia, and infection." (PMID 33859634, 2021). "In this study, we firstly showed that MUC5B promoter rs868903 was associated with the radiographic fibrosis extent in HRCT and reduced survival in a Chinese IPF cohort." (PMID 31653936, 2019). "Similarly, in patients with chronic hypersensitivity pneumonitis (cHP), the rs868903 variant of MUC5B was associated with fibrosis extent." (PMID 40999395, 2025). "MUC5B polymorphism wasnot detected in 10 (66.7%) of the fibrosis group." (PMID 36912407, 2023). "Similarly, MUC5B was also predominantly expressed in cholangiocytes, and has been associated with protection and regeneration of mucosal epithelium in airway disorders such as fibrosis and chronic obstructive pulmonary disorder." (PMID 38036513, 2023). "Studies have alsofound that HP patients are more likely to have shorttelomere lengths and minor alleles of the Mucin 5B(MUC5B) gene rs35705950, which are associatedwith fibrosis extent." (PMID 36912413, 2023). "By using IF staining, we further demonstrated over-secretion of MUC5B+ mucus in the conducting airway lumens of IPF patients, accompanied with 93.55% (29/31) IPF patients that had obvious MUC5B+ mucus plugs in alveolar regions surrounded by fibrosis." (PMID 35174169, 2021). "Single-cell analysis, histology, and qRT-PCR revealed that fibroblasts expressing high levels of fibrosis markers regulate STAT3 signaling in AT2 cells, which is accompanied by cystic organoid growth and MUC5B expression." (PMID 39578767, 2024). "In patients with IPF, overexpression of MUC5B in the distal airways is believed to impair mucociliary clearance and thus lead to excessive lung retention of xenobiotics or endogenous inflammatory debris, which may induce and sustain the development of fibrosis." (PMID 34529707, 2021).
viral infection (12 papers, 2010 to 2024). "Excessive mucus secretion occurs in response to viral infection and is associated with increased expression of mucin genes MUC5B and MUC5AC." (PMID 39538325, 2024). "It would be very interesting in the future to analyze by ex-vivo experiments of susceptibility to ANDV infection or viral infection inhibition in presence of purified MUC5B." (PMID 33224896, 2020). "In conclusion, MUC5AC and MUC5B were both induced during viral infections in COPD." (PMID 35239513, 2022). "Airway mucins MUC5AC and MUC5B are the predominant gel-forming mucins in COPD, and CS exposure and frequent bacterial or viral infection synergistically amplify MUC5AC levels." (PMID 35774797, 2022). "Unlike the filtrates from the mixtures of HIV-1 plus MUC5B and MUC7 from HIV negative individuals, these filtrates caused 100% viral infection of the CEM SS cells." (PMID 20946627, 2010). "The result demonstrated that irrespective of their CD4 count both MUC5B and MUC7 mucins from HIV patients, unlike those HIV negative patients, failed to inhibit HIV-1 activity and a 100% viral infection of the CEM SS cells was measured by the p24 antigen assay after a 30 min incubation period." (PMID 20946627, 2010).
lung adenocarcinoma (11 papers, 2012 to 2025). A carcinoma that arises from the lung and is characterized by the presence of malignant glandular epithelial cells. "Further analysis revealed that only MUC5B could stratify lung adenocarcinoma patients into high- and low-risk groups." (PMID 41409294, 2025). "We extended progression-free survival (PFS) analysis using TCGA survival data, revealing significant association between MUC5B and PFS in lung adenocarcinoma (p<0.05), reinforcing its lymph node metastasis relevance." (PMID 41409294, 2025). "Overall, these findings collectively suggest that MUC5B plays a pivotal role in facilitating lung adenocarcinoma cell proliferation, migration, invasion, and colony formation, underscoring its potential as a therapeutic target in LUAD." (PMID 41409294, 2025). "The positive signal of MUC5B was mainly localized in the cytoplasm of lung adenocarcinoma cells, showing a granular or diffuse brownish-yellow distribution." (PMID 41409294, 2025). "The IHC results showed that MUC5B expression was significantly higher in lung adenocarcinoma tissues with lymph node metastasis compared to those without metastasis." (PMID 41409294, 2025). "We collected tumor tissues from 65 patients with lung adenocarcinoma and performed immunohistochemical (IHC) staining to assess MUC5B expression." (PMID 41409294, 2025). "In this study, we investigated the overall protein profile and MUC5B expression in lung adenocarcinomas, the most common type of NSCLCs." (PMID 24176033, 2013). "The aberrant expression of MUC5B was further identified in 71.1% of lung adenocarcinomas in the TMA." (PMID 24176033, 2013). "The differential expression of MUC5B in lung adenocarcinomas suggests its role as a potential biomarker in the detection of adenocarcinomas." (PMID 24176033, 2013). "In our study, we found elevated expression of MUC5B in lung adenocarcinoma by iTRAQ labeling and further validated by IHC using lung adenocarcinoma TMAs." (PMID 24176033, 2013). "This is the case for MUC5B, which is expressed abnormally in gastric carcinomatous tissues and cell lines, and in lung adenocarcinomas." (PMID 23056409, 2012). "However, compared with these prior works, our study not only identified MUC5B as a critical gene driving LNM in lung adenocarcinoma but also constructed a MUC5B-centered predictive model for LNM." (PMID 41409294, 2025). "We hypothesize that MUC5B may promote lymph node metastasis in lung adenocarcinoma by modulating the expression of the GINS gene family, thereby enhancing DNA replication and cell cycle progression." (PMID 41409294, 2025). "In the iTRAQ labeling study, it seems that there is a loss of MUC5B expression in higher stage of tumors (stage II lung adenocarcinomas), however, we will not be able to draw a conclusion due to a small set of cases in our study." (PMID 24176033, 2013). "Our data demonstrates that MUC5B is abnormally expressed by most of tumors, and suggests that it may be a potential biomarker for lung adenocarcinomas." (PMID 24176033, 2013). "In this study, we investigated the protein profiles, including the expression of MUC5B in lung adenocarcinomas using highly sensitive iTRAQ labeling approach, and further validate our observations by immunohistochemistry (IHC) using lung adenocarcinoma tissue microarray (TMA)." (PMID 24176033, 2013). "Moreover, the high expression of MUC5B was significantly related to poor outcomes in lung adenocarcinoma and may increase the likelihood of post-operative lung cancer recurrence or metastases." (PMID 37770976, 2023). "The present study suggested that the combination of MUC5B and TTF-1 expression is useful for discriminating adenocarcinomas from squamous cell carcinomas, yielding prognostic significance in patients with lung adenocarcinoma." (PMID 25733373, 2015). "Additionally, the combined detection of MUC5B and TTF-1 can greatly improve the accuracy of detecting lung adenocarcinoma by distinguishing different cancer cell types." (PMID 40655139, 2025).